TET2 (tet methylcytosine dioxygenase 2)
Diseases named in the same sentence as TET2 in open-access papers (continued):
Sharing a sentence is not in itself a finding about the gene and the disease.
tumor (continued). "Together, these findings indicate that the tumor inhibition role of EMT/WNT pathway and TET2 is an intrinsic brake on cancer progression, which represents a potential therapeutic target for CRC." (PMID 41605908, 2026). "Previous studies have shown that TET2 mediates the IFN-γ/JAK/STAT signaling axis to regulate PD-L1 expression, lymphocyte infiltration dynamics, and anti-tumor immunity." (PMID 41356199, 2026). "Epigenetic dysregulation in TALL involves MYC-mediated control of TET1/TET2 enzymes, where TET1 promotes oncogenesis via ribosomal biogenesis, while TET2 acts as a tumor suppressor." (PMID 40781676, 2025). "5hmC, TET1, TET2, and DNMT3B were primarily expressed in the nuclei of tumor cells, while SDHB exhibited granular cytoplasmic staining." (PMID 41290745, 2025). "On the other hand, increased TET2 levels can protect cells from EMT and resistance to therapy, highlighting the importance of TET enzymes in tumor development." (PMID 40427015, 2025). "In turn, intratumoral infiltrating lymphocytes secrete IL-2 to activate tumor STAT5A signaling, which further synergizes with TET2 to epigenetically upregulate tumor cGAS, indicating a positive feedback loop." (PMID 38177099, 2024). "We identified TET1, TET2, and TET3 as pivotal players influencing tumor progression, prognosis, immune response, tumor microenvironment, and drug sensitivity." (PMID 39104395, 2024). "TET2 augmentation contributed to the CDKN2A promoter demethylation, tumor suppressor re-expression, and concomitant resistance to DNMT inhibitors in the DNMT1 gene deleted state." (PMID 39057134, 2024). "In fact, inactivation of TET2 and deletion of DNMT3A have proven to be efficient in potentiating anti-tumor immunity by adoptively transferred cells." (PMID 38321550, 2024). "To assess the DNMT3A and TET2 protein expressions in OSCC, we performed western blotting of six pairs of primary tumor and surrounding healthy tissue samples." (PMID 38246976, 2024). "Association with immunohistochemistry (Ki-67 labeling index) and sequencing certain tumor suppressing genes (HRPT2, TET2) improves the accuracy of the diagnosis." (PMID 36984449, 2023). "The expression of TET2/3 and p-STAT1/3 was also increased in tumor tissue in the α-KG + anti-PD1 group." (PMID 36854755, 2023). "Further, since apoptosis reduction is one of the critical features of chemotherapy-resistant tumor cells, we examined the expression of apoptosis-related proteins in HCC cells with different levels of TET2/PCAF." (PMID 36732324, 2023). "To understand the potential role of TET2 expression and TET2-mediated 5-hmC modification in LUAD, we first analysed the differences in TET2 expression and 5-hmC levels between adjacent normal tissues and tumours in 60 paired samples." (PMID 37667220, 2023). "A synergistic effect between TET2 and RHOA G17V in inducing tumor cell proliferation was discovered in mouse models of AITL with TET2 deletion and RHOA G17V mutation." (PMID 37188182, 2023). "IHC staining further showed increased protein levels of TET2, cGAS, STING and TBK1 in TET2-overexpressing tumours, in which the protein levels of STING and TBK1 were clearly decreased by RU.521 treatment." (PMID 37667220, 2023). "To provide clinical evidence for TET2-mediated mTORC1 suppression, we analyzed 371 liver hepatocellular carcinoma (LIHC) tumor samples from TCGA database." (PMID 37550284, 2023).
tumor (continued). "Eventually, our qRT-PCR results showed that tumor tissues had higher NOP2 and NSUN6 expression levels and lower TET2 expression than normal tissues of ccRCC samples." (PMID 35309925, 2022). "Several DNA5mC regulators were found to be significantly overexpressed in tumor tissues, including DNMT1, DNMT3B, TET2, TET3, MBD1, and SMUG1." (PMID 36425533, 2022). "The Sanguini diagram revealed the correlation between TET2 and the age, TMN stage (or tumor grade), and prognosis of patients." (PMID 35223782, 2022). "We further identify a SOX2:miR-10b-5p:TET2 axis that represses TET2 expression, represses 5hmC, increases 5mC levels, and induces GBM cell stemness and tumor-propagating potential." (PMID 35136034, 2022). "In TET2MT tumor cells, TET1 and TET3 partially compensate for TET2 activity and contribute to the pathogenesis of TET2MT hematopoietic malignancies." (PMID 36203205, 2022). "Collectively, these data show that enforcing active TET2 CD expression mitigates the tumorigenicity of MCF-7 cells and are consistent with previous work showing that both TET1 and TET2 reduce tumor growth in xenograft mice." (PMID 35351824, 2022). "Taken together, these clinical and molecular data show that TET2 downregulation by SOX2 drives GBM cell stemness and in vivo tumor growth." (PMID 35136034, 2022). "Further investigation illustrated that DNMT1/3A/3B, TDG, SMUG1, UNG, NEIL1, MDB3/4, ZBTB33, and UHRF1/2 were essentially upregulated in tumor samples, while TET2, MBD1, and MBD2 were downregulated in tumor samples." (PMID 35205097, 2022). "Whereas further experiments are required to determine the molecular underpinnings of 5-aza toxicity in TET2-silenced T-ALL cells, our results clearly identify TET2 as a potential tumor suppressor and, importantly, a therapeutic target in T-ALL." (PMID 34413196, 2021). "Given that TET2 knockout leads to intergenic DNA hypomethylation, it is possible that TET proteins also modulate the responsiveness of tumor cells to immunotherapy through similar mechanisms." (PMID 34885145, 2021). "Increased expression of both miR-92a-3p and miR-92a-5p and aberrant expression of TET2 was observed in NHL cell lines and tumour tissues, as well as disparate levels of dysfunctional promoter CGI methylation." (PMID 34899857, 2021). "One tumour sample displayed Reed-Sternberg-like cells during the histological examination, while our studies showed significantly decreased TET2 expression compared to other DLBCL and FL tumour samples, as well as compared controls considered." (PMID 34899857, 2021). "While TET2 appears to have a clear role as a tumor suppressor, the function of TET1 in oncogenesis is equivocal as a tumor suppressor vs a driving oncogene." (PMID 36618446, 2021). "We also identified two genes with significantly higher prevalence in the VTT tissues compared with the matched primary tumor tissues, including CELSR2 (30.43 vs. 4.00%, p < 0.05) and TET2 (17.39 vs. 0, p < 0.05)." (PMID 34249685, 2021). "The tumour/normal TL ratio was significantly correlated with the 5-hmC level (high vs. low; P = 0.043) and frequency of low expression levels of TET1, TET2, and TET3 (0 vs. 1-3; P = 0.043)." (PMID 33758594, 2021). "Increased TET2 mRNA expression was observed in both DLBCL (p = 0.0164) and FL (p = 0.0240) patient tumour biopsies compared to controls, and decreased methylation was observed in FL tumours compared to controls (p = 0.0300)." (PMID 34899857, 2021). "Differential expression of TET2 was seen across NHL cell lines and malignant tissues compared to controls, with specifically increased expression of TET2 in Mino, Raji, and Toledo cell lines alongside DLBCL and FL tumour tissue compared to controls." (PMID 34899857, 2021).
tumor (continued). "A possible explanation for this finding is TET2 overexpression in cells of some aggressive and indolent NHL subtypes is an innate immune response, involving tumour suppressor and DNA repair pathways, to the specific subtype of malignancy." (PMID 34899857, 2021). "Several other genes in our model have been independently verified as oncogenes (SPAG5, PARM1) or tumor suppressors (VEPH1, GLCE) in prostate or other cancers, showcasing the ability of our TET2-based model to capture these key changes." (PMID 33008340, 2020). "To investigate the role of TET2 in HCC progression, we determined the expression levels of TET2 in HCC clinical samples by immunohistochemistry (IHC) staining of tissue microarrays (TMAs), which contain 78 pairs of tumor and adjacent normal tissues." (PMID 33097695, 2020). "Our analysis during tumor development of KSHV (+) tumors detected promoter hypo-methylation and up-regulation of the demethylase Tet2 gene." (PMID 32603362, 2020). "Ten-eleven translocation 2 (TET2) is part of the TET family and is a tumor suppressor gene that is inactivated in a wide range of hematological malignancies." (PMID 33271790, 2020). "TET2 (ten-eleven translocation 2) expression was lower in ESCC than in normal mucosa and its expression in tumour tissue correlated with lymph node invasion." (PMID 32429269, 2020). "Tumor samples were classified as positive when the mRNA expression levels exceeded 0.580, 0.102, and 1.866 for TET1, TET2, and TET3, respectively." (PMID 31602281, 2019). "Knockdown of TET1 or ectopic expression of TET2 in T-ALL was associated with genome-wide changes in 5mC and 5hmC enrichment and decreased cell proliferation, suggesting a tumor promoting function of TET1, and a tumor suppressing role for TET2." (PMID 31266538, 2019). "Taken together, we conclude that ectopic expression of TET2 in T-ALL alters 5mC and 5hmC patterns and thus gene expression programs resulting in reduced tumor cell proliferation." (PMID 31266538, 2019). "We generated methylation profiles of TET1, TET2 and TET3 genes in tumor samples obtained from 233 patients with HNSCC; these included 57 hypopharynx, 44 larynx, 69 oral cavity, and 63 oropharynx tumor samples." (PMID 29849955, 2018). "We also provided evidences indicating that overexpressed STAT5 combines with TET2 to form complexes that bind to the FOXP3-TSDR, resulting in excessive demethylation in tumor-infiltrating CD4+ T cells." (PMID 30013992, 2018). "TET1 enzyme, along with TET2 and TET3, contributes to DNA demethylation through its conversion of 5mC to 5hmC and is considered to be a tumour suppressor, acting to prevent cell proliferation and tumour metastasis in human solid tumours." (PMID 28587163, 2017). "Some of the hypermethylated genes in TET2-wt CMML have been directly or indirectly related to cell cycle arrest, tumor suppression or myeloid differentiation (ZIC1, WT1, WNK2, MRPL41, POU4F2)." (PMID 22328940, 2012). "Moreover, HDVC activates TET2 and regulates the cyclic GMP‒AMP synthase (cGAS)/stimulator of interferon genes (STING) signaling pathway, facilitating tumor vascular normalization, improving the TME, and further boosting the efficacy of immunotherapy." (PMID 41403402, 2026). "Given its structural analogy to α-ketoglutarate (α-KG), we hypothesize that fumarate competitively inhibits TET2 activity, thereby promoting EMT in tumor cells via miR200a promoter methylation." (PMID 41356199, 2026). "There was no observed difference in mouse overall survival or tumor immune infiltration between mice receiving wild-type bone marrow and those receiving Tet2-null bone marrow." (PMID 39874138, 2025). "Research indicates that TET2 plays a role in activating IFN-γ-induced chemokine and PD-L1 gene expression by mediating the IFN-γ/JAK2/STAT1 signaling pathway, thereby contributing to an immunosuppressive tumor microenvironment." (PMID 40427015, 2025).
tumor (continued). "The TMA analysis revealed increased levels of CCNY, TET2, and phosphorylated PRC1 in tumor tissues." (PMID 40665337, 2025). "Combination of TET2 activator vitamin C and MC1R ligand α-MSH significantly dampens tumor growth." (PMID 40473594, 2025). "Conversely, DNMT1-mediated methylation silences chemokines such as CXCL9 and CXCL10, leading to reduced anti-tumor immune cell infiltration; the restoration of TET1 and TET2 can reverse this effect and improve the efficacy of immune checkpoint inhibitors (ICIs)." (PMID 41394878, 2025). "Tumor growth measurements indicate that neither VC nor anti–PD-L1 worked to inhibit tumor growth in the TET2-KO groups when compared with the PBS control." (PMID 39388288, 2024). "In contrast, Tet2 overexpression in combination with IL-2 stimulation led to more increase in Cgas expression than either alone, suggesting that TET2 synergizes with STAT5A signaling to promote tumor cGAS expression." (PMID 38177099, 2024). "In addition, OVA antigen presentation was largely uninduced by IFN-γ in the TET2-KO clones, emphasizing the critical role of TET2 in activating antigen presentation genes in B16-OVA tumor cells." (PMID 39388288, 2024). "Our findings uncover the role of tumor suppressor TET2 in anti-tumor immunity via cGAS-STING-mediated vascular normalization." (PMID 38177099, 2024). "Antigen presentation pathways were largely unaffected in the TET2-KO tumor tissue regardless of VC treatment." (PMID 39388288, 2024). "A similar result was observed for other tumor clusters in the TET2-KO groups as well (data not shown)." (PMID 39388288, 2024). "The cluster 9 and cluster 13 populations were modestly increased after VC treatment in the WT, but not in the TET2-KO, tumor background when comparing the relative ratio of different immune cell clusters." (PMID 39388288, 2024). "Based on the epigenetic regulation of tumor cGAS by TET2 synergized with STAT5A signaling, stimulating TET2 activity by VC triggers tumor cGAS-cGAMP-endothelial STING pathway activation and induces tumor vascular normalization, thereby potentiating immunotherapy efficacy." (PMID 38177099, 2024). "To determine whether VC stimulates antigen presentation gene expression in tumor cells, we analyzed the DEGs between VC-treated tumor clusters relative to PBS control in both WT tumors and TET2-KO tumors." (PMID 39388288, 2024). "This epigenetic and metabolic shift in the tumor microenvironment, as demonstrated in these mouse models, suggests that immune checkpoint blockade coupled with the IFN-γ-TET2 axis can surmount immunosuppression, thereby providing a strategy to counteract the resistance to IDH1 mutation inhibitors." (PMID 39156971, 2024). "Interestingly, lenvatinib enhances NAD+ metabolism in HCC cells by targeting the TET2 pathway, which increases NAD+ levels and induces tumor cell apoptosis." (PMID 39461979, 2024). "Consequently, IL-2 produced by infiltrating lymphocytes stimulates tumor STAT5A signaling, which, in turn, synergizes with TET2 to epigenetically elevate tumor cGAS expression, thereby establishing a positive feedback loop." (PMID 39107856, 2024). "Consistent with the previous GO pathway results, VC administration did not induce antigen-presenting gene expression in the TET2-KO groups, either the tumor cells or non-tumor cells." (PMID 39388288, 2024). "Finally, Genistein, a bioactive isoflavone present mainly in soybean products, decreases the TET2 and TET3 expression and delays TNBC tumor growth in vivo." (PMID 38203443, 2023). "We found the TETl, TET2, and TET3 protein levels in tumor tissues were significantly lower than those in para cancerous tissues, and the decrease of TET1 has a positive correlation with the decrease of 5-hmC in tumor tissues." (PMID 37266610, 2023). "Therefore, we detected the levels of 5-mC, 5-hmC, TETl, TET2, and TET3 in tumor tissues and the corresponding para cancerous tissues of 40 patients with HBV-related HCC." (PMID 37266610, 2023).
tumor (continued). "MenSC treatment increased the levels of TET2, BNIP3, and BNIP3L in the Huh7-SR xenograft tumours." (PMID 37005657, 2023). "Furthermore, we examined TET2, BNIP3, and BNIP3L protein levels in HCC-SR tumour tissues by performing immunohistochemical staining." (PMID 37005657, 2023). "This study aimed to identify the levels of 5-hmC, 5-mC, TETl, TET2, TET3, IDH1, and IDH2 in tumor and the adjacent tissues, so as to explore whether the 5-hmC is decreased in HBV-related HCC tissues and, if possible, to explore the associated mechanism." (PMID 37266610, 2023). "In contrast to other mutations such as TET2 and DNMT3A, which can occur in both tumor and nontumor cells of AITL patients, RHOA mutations appear to be limited to tumor cells, indicating that they play an important role in AITL pathogenesis." (PMID 38023160, 2023). "The role of TET2 in tumor resistance is not well studied, but the upregulation of TET3 has been shown to increase the expression of tumor suppressor genes, leading to the inhibition of growth and self-renewal ability in glioblastoma stem cells." (PMID 38067304, 2023). "Over-expression of TET2 Catalytic Domain (TET2-CD) increases the 5hmC levels, which induces and inhibits the expression of thousands of genes that inhibit cell proliferation and migration in MCF-7 BC cells, as well as tumor growth in vivo." (PMID 38203443, 2023). "However, loss of TET2 significantly decreased the ability of Vit-C to activate tumor-infiltrating CD8+ and CD3+ cells, indicating that TET2 is the primary target for Vit-C in enhancing the effectiveness of the anti-PD-L1 therapy." (PMID 35745630, 2022). "The authors observed low TET1 and TET2 in tumors capable of metastasizing to regional lymph nodes compared to patients with non-dissipated neoplastic disease." (PMID 35409163, 2022). "Accordingly, deletion of Tet2 failed to fully activate SMM-related genes in tumor-conditioned macrophages even with Bcl6 overexpression." (PMID 36542153, 2022). "Collectively, these results suggested that TET2 does not play a significant intrinsic role in RCC cell proliferation in vitro or tumor growth in vivo." (PMID 35173532, 2022). "Furthermore, ROC analysis was performed to determine the efficiency of TET2 in predicting the 1-, 3-, and 5-years OS, DFI, PFI, and DSS in patients with selected tumor types from TCGA database." (PMID 35223782, 2022). "A multivariate analysis also identified TET2 overexpression as a prognostic factor independent of the histological type, tumour size, nodal involvement and intrahepatic metastasis." (PMID 34905094, 2022). "Based on the results of preclinical studies, future randomized clinical trials should be designed to evaluate vitamin C activity in specific tumor molecular subtypes, such as those characterized by HIF-1α over-expression and TET2, L2HGDH, IDH1/2, or WT1 altered pathways." (PMID 33804775, 2021). "Then, we demonstrated that TET2 depletion promoted HCC cells stemness, tumor growth and metastasis." (PMID 34019487, 2021). "In addition, in HNSCC tumor tissues, the expression level of the m5C eraser TET3 was significantly elevated, while that of TET2 was downregulated." (PMID 33912441, 2021). "By this means, recently published data showed that downregulation of key proteins involved in T cells terminal differentiation and exhaustion such as NR4A, TOX/TOX2, TET2, Regnase1, or PTPN22 increased T cell-based treatment half-life and improve anti-tumor performance." (PMID 33287392, 2020).